PSMB5 (proteasome 20S subunit beta 5)
Diseases named in the same sentence as PSMB5 in open-access papers (continued):
Sharing a sentence is not in itself a finding about the gene and the disease.
hematologic malignancy (1 paper, 2022). "Carfilzomib and Bortezomib, used to treat hematologic malignancy, have repurposing potential against PSME3 and PSMB5 dysregulation." (PMID 36293493, 2022).
PSMB5 also shares sentences with these, for which no sentence is quoted: Alpha-thalassemia (21 papers); infection (12); fragile X syndrome (10); Intellectual disability (10); synovial sarcoma (9); autism (6); fragile X-associated tremor/ataxia syndrome (6); lung carcinoma (5); ataxia syndrome (4); Tremor (4); α-thalassemia (4); Cirrhosis (3); developmental delay (3); Immunodeficiency (3); neurological disorders (3); pancreatic cancer (3); Parkinsonism (3); Rett syndrome (3); amyotrophic lateral sclerosis (2); autoimmune disease (2); colorectal cancer (2); epilepsy (2); genetic disorder (2); glioblastoma (2); head and neck squamous cell carcinoma (2); heart diseases (2); Hypercholesterolemia (2); liver disease (2); lymphoma (2); mantle cell lymphoma (2).
A further 113 diseases each share a sentence with PSMB5 in 2 papers or fewer.